IL6 (interleukin 6)
Diseases named in the same sentence as IL6 in open-access papers (continued):
Sharing a sentence is not in itself a finding about the gene and the disease.
Hepatitis (continued). "In both α-GalCer- and Con A-induced murine hepatitis models, CD160−/− mice suffered from severe inflammation with elevated IL-4, IL-6, IFN-γ, and TNF-α and could not fully recover from lethal Con A challenge." (PMID 31332204, 2019). "However, the concentrations of plasma IL-6 and IL-1β in ASC were not different from those of HBV infected individuals with hepatitis (CHB &AHB)." (PMID 21639870, 2011).
Cirrhosis (215 papers, 2009 to 2026). A chronic disorder of the liver in which liver tissue becomes scarred and is partially replaced by regenerative nodules and fibrotic tissue resulting in loss of liver function. "A recent study showed elevated GFAP in the blood of patients with hepatic encephalopathy associated with cirrhosis, which was correlated with ammonia and IL6 levels in serum." (PMID 38606159, 2024). "Serum IL6 is associated with poor outcomes in patients with cirrhosis using blood levels in prior studies." (PMID 39733165, 2024). "On the other hand, activated intestinal macrophages in patients with cirrhosis have been associated with an increased intestinal permeability enhancing the translocation of pathogens by releasing interleukin-6 and nitric oxide." (PMID 37004869, 2023). "IL-6 predicts the risk of the first decompensation in patients with compensated cirrhosis and also 1-year liver-related mortality predictor or the need for liver transplantation in those with decompensated cirrhosis." (PMID 37304826, 2023). "Upstream regulator analysis identified HNF-4α and IL-6 as the most important regulators underlying the observed serum proteome changes in patients with decompensated cirrhosis." (PMID 36652164, 2023). "Of note, bacterial translocation in decompensated cirrhosis is also known to generate high IL-6 concentrations and is associated with acute-on-chronic liver failure (ACLF) and platelet activation." (PMID 34432848, 2021). "For instance, constitutive STAT3 activation leads to increased interleukin-6 expression, which is the main mediator of the acute phase of HB and HB-associated cirrhosis." (PMID 32024508, 2020). "HCV-related cirrhosis is associated with more elevated serum concentrations of monocyte-derived markers (sCD14 and IL-6)." (PMID 25775475, 2015). "IL-6 has been shown to predict the first decompensation episodes and 1-year mortality in decompensated liver disease, and is associated with liver fibrogenesis in stable cirrhosis and portal hypertension." (PMID 37973887, 2023). "ALD-cirrhosis was associated with IL-6, CCL27 and G-CSF and NAFLD-cirrhosis with LIF and CCL25." (PMID 36230823, 2022). "However, only IP-10 and IL-6 were independently associated with Child-Pugh B cirrhosis (CTP 7–9) with high accuracy." (PMID 32587340, 2020). "Moreover, it was shown that TNF-α and IL-6 levels are elevated in cirrhosis, and these enhancements are associated with HC intensification." (PMID 32128089, 2019). "Furthermore, IL-6 also appeared to be the best predictor of infections in patients with cirrhosis among all diagnostic indicators in the ROC curve." (PMID 31915467, 2019). "These cytokines fuel MASLD: TNF-α promoted liver lipid buildup, while IL-6 accelerated progression to cirrhosis or cancer." (PMID 41368575, 2025). "Serum IL-6 significantly increased from 2.32 pg/ml to 3.03 pg/ml (p = 0.02) at 1 year in patients with cirrhosis and CSPH." (PMID 39850960, 2025). "In fact, an exaggerated in vitro response to bacterial products has been reported in patients with cirrhosis compared to healthy controls, particularly in the production of interferons, IL-6 and IL-8." (PMID 40431335, 2025). "Systemic inflammation has been well-recognized in liver cirrhosis, where knowns EC stimulants such as VEGF, TNF-α, IL-6, IL-8, and IL-1ra, are significantly elevated in the plasma of patients with cirrhosis." (PMID 39761260, 2025). "In the decompensated phase of cirrhosis, activated intestinal macrophages secrete TJ-modulating factors like nitric oxide (NO) and IL-6, contributing to the disruption of the intestinal epithelial barrier." (PMID 40444006, 2025). "It should be noted that IL-6 influences the immune response by regulating T cell differentiation, further complicating the inflammatory environment in cirrhosis." (PMID 40806358, 2025). "This is in agreement with earlier studies linking IL-6 to SI, hepatic decompensation, and renal impairment in cirrhosis and ACLF patients." (PMID 41189884, 2025).
Cirrhosis (continued). "Quantitative PCR revealed that FMT from HBV-cirrhosis patients upregulated the hepatic mRNA expression of inflammatory cytokines, including IL-6, TNF-α, and IL-18." (PMID 40642988, 2025). "Even sterile ascites of patients with decompensated cirrhosis often contains IL-6 due to local macrophage priming." (PMID 38962151, 2024). "In a cohort of 51 patients with a diagnosis of ACLF and decompensated cirrhosis, the degree of SI (levels of IL-10, IL-6, and TNF-α) determines the outcome." (PMID 39337069, 2024). "The study’s main strength lies in validating the diagnostic value of serum endocan, along with widely used biomarkers, such as PCT and IL-6, for detecting OF in hospitalized patients with cirrhosis." (PMID 39724169, 2024). "In cirrhosis patients, activated macrophages determine NO, IL-6, and IL-8 production under bacterial stimulation, affecting the gut barrier function." (PMID 38473721, 2024). "The results indicated that IL-6, IL-10 and IL-8 were higher in cirrhosis patients than in healthy controls." (PMID 38413535, 2024). "Chronic exposure to elevated levels of circulating cytokines, such as tumor necrosis factor-alpha (TNF-α) and interleukin-6 (IL-6), plays a pivotal role in the inflammatory milieu that characterizes cirrhosis." (PMID 39859028, 2024). "SB reduced the serum TNF-α and IL-6 levels in experimental carbon tetrachloride-induced cirrhosis in rats and also reduced the level of CRP in one RCT with decompensated cirrhosis patients." (PMID 39203520, 2024). "Patients with cirrhosis have high systemic inflammation (TNFα, CRP, and IL-6) that is associated with poor outcomes." (PMID 39733165, 2024). "It is worth noting that CD169+ monocytes from patients with cirrhosis highly express both IL-10 and IL-6." (PMID 38413535, 2024). "The presence of ascites, serum endocan, IL-6, NLR, creatinine, sodium, TB, and albumin was associated with OFs in cirrhosis." (PMID 39724169, 2024). "Persistent alterations are observed only in chronic HCV patients with cirrhosis, displaying a distinct long-term pattern compared to IL-10, IL-22, TNFα, IFNγ, and IL-6." (PMID 39578604, 2024). "TNF-α, IL-1β, IL-6, and NF-κB are key players in orchestrating inflammatory responses that can lead to liver damage, fibrosis, and cirrhosis." (PMID 38999918, 2024). "SB reduced the liver expression of the TNF-α and IL-6 genes in carbon tetrachloride-induced cirrhosis in rats." (PMID 39203520, 2024). "For instance, an observational study revealed elevated levels of proinflammatory cytokines, such as IL-6 and IL-8, in cirrhotic patients compared to healthy controls, with the levels increasing as cirrhosis progresses." (PMID 39457577, 2024). "IL-6, with a cut-off point of 37 pg/mL, was an independent indicator of 28-day mortality in patients with cirrhosis." (PMID 39724169, 2024). "Infused albumin can also exhibit protective effects by binding to the cirrhosis-induced proinflammatory cytokines TNFα and IL6." (PMID 38551716, 2024). "IL-6 levels, on the other hand, were significantly higher in patients with decompensated cirrhosis (p = 0.02)." (PMID 37304826, 2023). "Cytokine levels of IFN-α2, IFN-γ, TNF-α, IL-6, IL-8, IL-10, IL-17A, IL-18, IL-23, and IL-33 were significantly elevated in patients with decompensated cirrhosis compared to patients with compensated cirrhosis." (PMID 38077228, 2023). "It would be worthwhile to study the levels of IL-6 and other inflammatory cytokines in mesenteric lymph of patients with cirrhosis with varying severity and correlate them with duodenal PDPN scores and mortality." (PMID 37304826, 2023). "Patients with compensated cirrhosis demonstrated increased basal and LPS-induced production of IL-6 compared to healthy controls and patients with more advanced disease (Child-Pugh class B & C)." (PMID 37928515, 2023). "In chronic inflammation of the liver (cirrhosis), hepcidin production is interceded by interleukin-6 (IL-6) dependent and IL-6 independent pathways." (PMID 37337504, 2023).
Cirrhosis (continued). "Our findings support IL-6 as a marker of disease severity in cirrhosis, as it was significantly elevated in our deceased participants." (PMID 37973887, 2023). "It has also been shown that both endotoxin and IL-6 can increase PVR, causing cirrhosis leading to PH." (PMID 37449201, 2023). "Upregulation of inflammatory factors such as IL-6 in cirrhosis enhances the activation of the IL-6/AMPK/FoxO3 axis." (PMID 37881635, 2023). "Another study of patients with cirrhosis revealed serum IL-6 and CRP levels as independent predictors of mortality and liver transplantation." (PMID 37799767, 2023). "Sequentially increasing numbers of M-MDSC with disease progression from compensated cirrhosis to AD/ACLF underlie the low TNF-α/IL-6 responses in AD/ACLF patients." (PMID 36926073, 2022). "Further, oral capsule FMT was correlated with decreased lipopolysaccharide (LPS) activity and reduced interleukin-6 (IL-6), two inflammatory mediators that can worsen cirrhosis." (PMID 36569149, 2022). "In line with previous findings, markers of inflammation (CRP, leukocytes and IL-6) were significantly elevated in patients presenting with decompensated cirrhosis in this cohort." (PMID 34654829, 2021). "Immunohistochemistry in decompensated cirrhosis patients showed colocalization of IL-6 with CD68+ iNOS+ Mφ and IL-6 was predominantly present in CD11c- cells." (PMID 33390844, 2021). "The serum levels of NF-ĸB, TNF-α and IL-6 are indicators of inflammation in the cirrhosis and they were increased significantly in the BDL group compared to the control group (p < 0.01)." (PMID 34567144, 2021). "The HCC timepoint was characterized by a significant increase in interferon-gamma (IFN-γ), tumour necrosis factor alpha (TNF-α), IL-6 and IL-17 compared to inflammation and cirrhosis timepoints (all P < 0.05)." (PMID 33858327, 2021). "The serum NF-κB, TNF-α and IL-6 levels of all groups in the cirrhosis model formed by bile duct ligation (BDL) in rats (n = 6; mean ± SD)." (PMID 34567144, 2021). "To conclude, we provide evidence entirely from human experimentation that demonstrates PGE2, acting via its EP4 receptor, downregulates monocyte TNFα and IL6 production in decompensated cirrhosis and reduces monocyte HLA-DR expression." (PMID 34825153, 2021). "IL-6 present in the inflammatory context, commonly boosted by bacterial translocation in cirrhosis, contributed to Th17 differentiation, skipping the Treg induction achieved under homeostatic conditions." (PMID 32429209, 2020). "This study evaluates the prognostic role of ascitic interleukin 6 in 64 patients with cirrhosis admitted to our intensive care unit (ICU)." (PMID 32899730, 2020). "IL-6 strongly correlates with the development of renal impairment and mortality in patients with cirrhosis and bacterial peritonitis." (PMID 33302342, 2020). "Levels of IL-6 were significantly increased in cirrhosis and cirrhosis-PVT pigs in comparison with the control group." (PMID 32351989, 2020). "It is assumed that cytokines play central roles in the progression from chronic liver injury to fibrosis/cirrhosis and several pro-inflammatory cytokines (such as IL6, and TNFα) correlate with disease severity." (PMID 32813194, 2020). "TNF-α/IL-6 responses to lipopolysaccharide were attenuated in monocytes from patients with cirrhosis (n = 96) compared with controls (n = 27) and decreased in parallel with disease severity." (PMID 31822557, 2020). "This in vivo study further demonstrated that elevated IL-6 level exerted a critical role in cirrhosis and thrombosis promotion." (PMID 32351989, 2020). "This study primarily demonstrates the prognostic accuracy of ascitic interleukin 6 (IL-6ascites) in critically ill patients with cirrhosis and acute-on-chronic liver failure (ACLF)." (PMID 32899730, 2020). "Interleukin 6 (IL-6) as a potential inflammatory marker stimulated PVT-mediated inflammation activation in cirrhosis." (PMID 32351989, 2020).
Cirrhosis (continued). "Baseline ascitic interleukin 6 performed well in predicting 3-month mortality in patients with decompensated cirrhosis (area under curve (AUC) = 0.802), as well as in patients fulfilling ACLF-criteria (AUC = 0.807)." (PMID 32899730, 2020). "IL-6 as a potential inflammatory marker stimulated PVT-mediated inflammation activation in cirrhosis." (PMID 32351989, 2020). "One study that compared cytokine levels in biliary atresia children with advanced cirrhosis with those in healthy children found anti-inflammatory cytokines IL-10 and IL-6 to be elevated." (PMID 30740106, 2019). "All of them except MMP2 were up-regulated in the cirrhosis condition being IL-6 the gene showing the largest extent of up-regulation." (PMID 31233564, 2019). "Excess adipose tissue causes low-grade systemic inflammation through the release of inflammatory cytokines such as Interleukin-6 (IL-6) and Tumour Necrosis Factor-ɑ (TNFɑ) resulting in chronic hepatic inflammation, cirrhosis and fibrosis." (PMID 30819129, 2019). "Comparison of each of these three HCC subgroups with cirrhotic patients revealed significantly higher AFP (p = 0.000) and IL-6 (p = 0.000) levels in each subgroup, as compared with cirrhosis cases." (PMID 29963457, 2018). "In other studies, it was observed that certain polymorphisms in IL-6 or its promoter are associated with lower rate of spontaneous clearance, and increased risk of HCC in patients with CVH-related cirrhosis." (PMID 29033929, 2017). "Positive associations of CRP, IL-6 and LBP have been reported before by others; however, in these studies, patients suffered from severe liver disease e.g. cirrhosis with infection." (PMID 28880885, 2017). "The highest concentration of interleukin-6 was observed in patients with decompensated cirrhosis (14.55 ± 12.51 pg/mL in stage C and 10.38 ± 9.96 pg/mL in stage B) whereas the lowest one in the control group (0.12 ± 0.41 pg/mL)." (PMID 28430124, 2017). "In this study, IL-8, together with IL-6, was higher in both patients with stable and those with decompensated cirrhosis and stayed high after development of acute-on-chronic liver failure." (PMID 28299346, 2017). "A similar study has shown CCl4-induced IL-6 activation is associated with an increase in MEK5, ERK5, JAK, and STAT3 expression prior to cirrhosis." (PMID 26062544, 2015). "Patients with cirrhosis showed significantly higher concentrations of serum sCD14 (p = 0,024) and IL-6 (p = 0,036) than those with chronic hepatitis." (PMID 25775475, 2015). "The changes found in nitrates, plasma cGMP, basal cGMP in lymphocytes and SNAP-induced cGMP increase, as well as IL-6, IL-18 and ammonia, were consistent with described changes in cirrhosis." (PMID 26420028, 2015). "IL-6 has been considered to exert a profibrogenic and mitoinhibitory influence on the development of cirrhosis." (PMID 26448742, 2015). "Data of our work have demonstrated that both sCD14 and IL-6 are even more increased in those HIV-infected patients with HCV-related cirrhosis." (PMID 25775475, 2015). "Th17 cells produce IL-6 and IL-17, which promote chronic liver inflammation, leading to the occurrence of cirrhosis." (PMID 25323532, 2015). "Higher IL-6 concentrations were also found in the group with class C liver cirrhosis in comparison with the group with class A cirrhosis." (PMID 26448742, 2015). "Most patients with advanced cirrhosis have chronic elevation of proinflammatory cytokines, such as IL-6 and TNF-alfa and endotoxins, which represent a chronic low-grade inflammatory state." (PMID 25279659, 2014). "The aim of our study was to assess a possible association between plasma inflammatory biomarkers (CRP, IL-6, soluble CD14) and the extent of fibrosis or cirrhosis using a FibroScan® in HIV/HCV co-infected patients." (PMID 23527135, 2013).